IL2 (interleukin 2)
Diseases named in the same sentence as IL2 in open-access papers (continued):
Sharing a sentence is not in itself a finding about the gene and the disease.
tumor (continued). "Moreover, the anti-tumor effects and survival rates in tumor bearing mice were significantly enhanced when IL-2 and IL-12 were delivered simultaneously using a single vaccine viral vector (Poxvirus/vaccinia viral vector) along with the tumor antigen." (PMID 21211062, 2011). "Vaccinia virus-induced inhibition of T cell proliferation was seen but could be reversed by adding IL-2 and IL-12 to the vaccinia constructs, and the vaccinia-cytokine strategy led to profound local tumor regression." (PMID 24213115, 2011). "Furthermore, there was an increased secretion of some anti-inflammatory cytokines, such as IL-1ra, and of cytokines with anti-tumour effect, such as IL-2 and IL-15." (PMID 20717114, 2010). "Thus, even in the setting of advanced ovarian tumors, CD8+ T cells mounted potent anti-tumor responses provided that IL-2/IL-15 signaling pathways were intact." (PMID 21203522, 2010). "Bergmann and co-authors used cell culture techniques with weak doses of IL-2, IL-10, and IL-15 to show that the tumor microenvironment generated Tr1 cells with a phenotype distinct from nTregs and that these cells abolished autologous responders proliferation via the secretion of IL-10 and TGF-β." (PMID 21437225, 2010). "Furthermore, IL-2 activated NK cells suppressed significantly the secretion of VEGF from tumor cells." (PMID 20661281, 2010). "In addition to its role as a global tumor suppressor miRNA, we also provide data to show that chicken IL-2 is a direct target for miR-26a." (PMID 20441582, 2010). "Adoptive transfer of tumor specific T cells in cancer immunotherapy translational studies has previously emphasized the transfer of highly differentiated, end stage effector T cells from in vitro IL-2 supported expansion cultures." (PMID 21034498, 2010). "Importantly, the proliferation and anti-tumor activity of the transferred CD8+ T cells was entirely dependent on IL-2/IL-15 signaling, as demonstrated by genetic disruption of the IL-2 receptor alpha (CD25) or beta (CD122) subunits." (PMID 21203522, 2010). "IL-2 is a cytokine commonly used in studies of tumor immunotherapy." (PMID 20936120, 2010). "The goal of a subsequent proof-of-concept phase II clinical trial is to analyze the efficacy of TKD/IL-2-activated NK cells in NSCLC patients following radiochemotherapy as this has been shown to enhance the density of Hsp70 membrane expression on tumor cells (unpublished observations)." (PMID 21179573, 2010). "Other studies suggest that the recruitment of immune cells induced by IL-2 administration at the tumour site could be also because of an indirect affect of IL-2 through MCs activation." (PMID 19935800, 2009). "The il-2 affects proliferation and maturation of effector cells, enhancing the function of natural killer T cells, generating lymphokine-activated killer cells, and stimulating T-cell and B-cell growth, resulting in a reduction in tumour growth." (PMID 19478896, 2009). "We hypothesized that EMD 273063 would bind to GD2 on tumor cells; its IL2 moiety would then activate T and NK cells, which would release a secondary wave of cytokines, orchestrating an antitumor immune response." (PMID 19640287, 2009). "The tri-cell complex of T-lymphocytes, tumor cells and accessory cells induces efficient tumor cell killing, which results from an activating "crosstalk" via cytokines (like e.g. IL-2, IL-12 and TNF-α) and costimulatory molecules between different immune cell types." (PMID 19216794, 2009). "The reasons for this outcome might relate to the study design in which we evaluated initial tumor responses two weeks after completing the first course of IL-2, selected in order to continue booster immunizations in a timely manner." (PMID 19128501, 2009). "A synergistic anti-tumor effect has been observed when TNF-α is combined with IL-2." (PMID 19570195, 2009). "The more tumor-infiltrating lymphocytes were also observed in the group of IL-2 adding at priming." (PMID 19901991, 2009).
tumor (continued). "We found that the anti-tumor activity of liqi might also be related to its regulatory effects on IL-2 and TNF-α, both of which play important roles in cancer therapy." (PMID 19570195, 2009). "Since Tregs may suppress tumor rejection by effector T cells and because IL-2 can promote Treg activity, we evaluated the frequency and functional activity of Tregs in our patients." (PMID 19128501, 2009). "We hypothesized that targeted delivery of IL2 to the tumor microenvironment using immunocytokines would limit toxicity and increase efficacy of IL2-based therapies." (PMID 19640287, 2009). "An explanation for this might be that the tumor has escaped the control mediated by TKD/IL-2-activated NK cells in vivo." (PMID 19549307, 2009). "However, in vitro incubation of PBMNC with TKD/IL-2 initiated a significant anti-tumor reactivity against the classical NK target K562 and also the autologous tumor." (PMID 19549307, 2009). "On the basis of histological features, the tumours were classified as epithelioid in 46 patients (76.7%), biphasic in 9 patients (15%) and sarcomatoid in 5 patients (8.3%) in the group of patients treated with preoperative IL-2." (PMID 19935800, 2009). "The induction of humoral and T cell immunity in this trial might relate to the underlying tumor histology, since RCC is known to be more immunogenic than other tumors or could be due to the adjuvant effects of high-dose IL-2." (PMID 19128501, 2009). "Moreover, four repeated re-infusions of purified TKD/IL-2-activated NK cells have been shown to eradicate the primary tumor and prevent metastasis in a xenograft tumor mouse model of human pancreatic cancer." (PMID 19549307, 2009). "The ability of IL-4 to inhibit IL-2 gene transcription has been confirmed by other researchers, suggesting that the elevation of IL-4 production during an ongoing immune response to tumor can down-regulate Th1 cytokine production." (PMID 19138398, 2009). "Importantly, effector CD8+ T cells generated in vitro in the presence of IL-2 at the priming stage proved to be fully functional in anti-tumor activity in vivo." (PMID 19901991, 2009). "Whether directing IL2 to the tumor environment is the most appropriate way to enhance local immunity will require further study." (PMID 19640287, 2009). "We also included four patients with papillary histology in the trial since these tumors express 5T4, but these tumor are also more resistant to IL-2, which may have influenced our results." (PMID 19128501, 2009). "IL-2 can induce the proliferation of activated T- and B-cells, enhance NK cytotoxicity, and increase the killing activity of monocytes and macrophages for tumour cells and bacteria." (PMID 19019236, 2008). "Furthermore, the cytokines IL-2, IL-4, TNFα and IFNγ have been shown to inhibit tumor-induced angiogenesis in some animal models by inhibition of tumor stroma formation." (PMID 19578507, 2008). "Furthermore, elimination of Tregs by IL-2-conjugated to diphtheria-toxin (ONTAK) enhanced vaccine-mediated anti-tumor immunity in cancer patients." (PMID 18294387, 2008). "Indeed, the tumorigenicity of viable Neuro-2A tumour cells in A/J mice was significantly reduced when coadministered with AJ-IL2/IL12 and Neuro-IL2/IL12 vaccines, with five of six mice in each vaccine group failing to develop tumours." (PMID 17595664, 2007). "In groups of mice (n=10) monitored for several months to study the long-term effect of vaccination on established tumours, only three of 10 mice (30%) in the group treated with the Neuro-IL2/IL12 vaccine and one of 10 mice (10%) in the group treated with the AJ-IL2/IL12 vaccine developed tumours." (PMID 17595664, 2007). "The IL-2 concentration in the control group was 24.13 ± 15.12 pg/ml, but below 15 pg/ml in groups A and C. Hence, there were significant differences between each tumor group and the control group (P < 0.05)." (PMID 17338814, 2007).
tumor (continued). "Autologous fibroblasts transduced with IL-2 and mixed with autologous irradiated tumour cells have been used in phase I trials to treat colorectal carcinoma, and IL-12-transduced autologous fibroblasts have been used to treat melanoma, both with promising results." (PMID 17595664, 2007). "Neuro-2A cells were engrafted in the left flank of A/J mice and when tumours were palpable (∼3 days), mice were vaccinated every 2 days for a total of three doses with Neuro-IL2/IL12 or AJ-IL2/IL12 cells (n=16 per group) or with RPMI medium (n=6), by i.t. injection." (PMID 17595664, 2007). "Transfection of Neuro-2A cells with IL-2 and IL-12 abolished their tumorigenicity in syngeneic A/J mice, and when injected into established tumours provoked an antitumour immune response involving CD8+ and CD4+ T cells, which led in some cases to complete tumour eradication." (PMID 17595664, 2007). "Finally, it is not clear what are the levels of cytokines able to discriminate normal and pathological situation and what is the significance of cytokines modifications during the tumor progression or during some biological therapy such as IL-2 therapy." (PMID 17953739, 2007). "Tumour-specific and progression-free survival were longer in IL-2-treated patients." (PMID 17031403, 2006). "Some authors hypothesised that soluble CRP prevents recognition and binding of tumour cells by IL-2-activated effector cells." (PMID 16940978, 2006). "Mice treated with both IL-21 and IL-2 exhibited the best anti-tumor response." (PMID 16772043, 2006). "A total of 98 tumour biopsies were analysed (IL-2/HDC, n=47 and IL-2, n=51)." (PMID 16434984, 2006). "However, combination therapy with IL-21 and IL-2 resulted in the highest long-term (>150 days) tumor-free survival frequency of 46%." (PMID 16772043, 2006). "However, immunological manipulation using interleukin-2 (IL-2) mediate durable tumour regression in 5–10% of patients lasting 5 and 10 years, and this subgroup of patients are probably cured." (PMID 16136045, 2005). "The tumour-specific T cells were then re-infused and supported with high-dose IL-2 infusions." (PMID 16251873, 2005). "However, only two patients had tumour responses while on the vaccine alone, whereas the other 10 demonstrated objective tumour regression following the combination with IL-2 (two CR, eight PR), lasting for a median duration of 6 months (range 3–50 months)." (PMID 14970852, 2004). "Likewise, exogenous IL-2 has been administered in the context of tumor antigen vaccination as well as in nearly every clinical application of adoptive transfer to provide helper function." (PMID 15566571, 2004). "The in vitro assay of IFN-γ production may not be fully reflective of the in vivo capacity of T cells to mediate tumor regression because CD4+ T cells cultured with IL-2 plus IL-7 had only 2% IFN-γ positive cells despite equivalent in vivo anti-tumor efficacy." (PMID 15566571, 2004). "The relatively high RR we have witnessed when IL-2 was given following immunisation suggests that the whole tumour vaccine may have generated tumour-reactive T-cell subsets." (PMID 14970852, 2004). "Notably, the tumour shrinkage induced by IL-2 was a lengthy process that continued months after the last course of high-dose IL-2, with no additional treatment." (PMID 14970852, 2004). "At 2 days after intratumoral administration of AdB7-1/IL-2, both E2-exposed tumours and placebo tumours had increased levels of IFN-γ compared with tumours injected with the control vector Addl70-3, 24±0.6 pg mg−1 tumour in AdB7-1/IL-2 vs 3±0.04 pg mg−1 tumour with the control vector." (PMID 12865933, 2003). "Tumour cells cultured alone produced less than 15 pg ml−1 IL-2." (PMID 12698199, 2003). "However, efficient antitumour protection (83%) were achieved with 118 ng IL-12 and 20 ng IL-2, while for 50% tumour growth inhibition a minimal 12 ng IL-12 and 2 ng IL-2 was required." (PMID 12771934, 2003).
tumor (continued). "Indeed, on the histology of biopsies taken from IL-2-treated metastases, we found a dense intra- and peritumoral lymphocytic infiltrate surrounding and infiltrating the areas of necrotic tumour cells." (PMID 14583759, 2003). "Also, patient clinical trials using IL-2 gene-modified autologous tumour cells have shown antitumour responses with antibody production and MHC-restricted cytotoxicity against autologous tumour cells." (PMID 12771934, 2003). "A second cytokine, such as IL-2, that is capable of clonally expanding activated T cells, may be vital for strengthening the immune response against the tumour and achieving long-term immunity." (PMID 12771934, 2003). "It is of interest whether or not TCR and HLA molecules are involved in the cytotoxic mechanism of the autologous tumour-reactive CD4+ Th1 killer lymphocytes induced with OK-432 plus IL-2." (PMID 14612896, 2003). "Manipulating the immune system by interleukin-2 (IL-2) based immunotherapy may induce durable tumour regression in metastatic renal cell carcinoma (mRCC)." (PMID 12107842, 2002). "The aim of the present study was to analyse lymphocyte subsets in consecutive peripheral blood samples and consecutive tumour tissue core needle biopsies performed before and during interleukin-2 based immunotherapy, and to correlate the findings with objective response and survival." (PMID 12107842, 2002). "The hypoxic fraction of the EMT6/IL-2 tumours growing in vivo was markedly decreased relative to parental EMT6 tumours thus the increased sensitivity results from the increased vascularity we have previously observed in these tumours." (PMID 10732769, 2000). "IL-2 and histamine in combination significantly reduced tumour growth." (PMID 10952789, 2000). "Tumours on one flank were irradiated (6 Gy once daily for 3 days to a total dose of 18 Gy) beginning 1 week after the onset of treatment with histamine and/or IL-2." (PMID 9579825, 1998). "However, we observed the selective recruitment, localization and arrest of IL-2-activated splenocytes (P < 0.05) into the tumour microcirculation, and the subsequent extravasation of cells into the tumour intestitium in some instances." (PMID 9413944, 1997). "When both IL-2 and autologous tumour cells in mixed lymphocyte tumour cultures (MLTCs) were used for stimulation, a dramatic increase in number (0.1) and in specific lytic activity (46%) could be measured." (PMID 7981054, 1994). "In particular, the association with the pineal neurohormone melatonin (MLT) has been shown to cause tumour regressions in neoplasms that are generally non-responsive to IL-2 alone." (PMID 8286206, 1994). "A study of activation of the cytokine network by interleukin 2, IL-2, may provide a rationale for devising cytokine combination and cytokine antagonist treatments with increased anti-tumour efficacy and decreased toxicity." (PMID 8439502, 1993). "The data accumulated in animal models and, more recently, also with human tumour cells indicate that the IL2 gene may be successfully inserted into neoplastic cells." (PMID 1457368, 1992). "Interleukin-2 (IL-2) treatment induces other cytokines such as tumour necrosis factor (TNF) TNF may mediate some of the anti-tumour activity of IL-2, but conversely, may contribute to its dose limiting toxicities." (PMID 1333789, 1992). "This study indicates that impairment of lymphocyte proliferation by tumour physico-chemical conditions may be a factor in the relatively poor success rate of IL-2/LAK cell immunotherapy." (PMID 1419598, 1992). "The inhibition of LAK cell stimulation by tumour cells may partially explain the failure of adoptively transferred LAK cells and IL-2 therapy to cause tumour regression in man." (PMID 2785396, 1989).
tumor (continued). "In an intraperitoneal tumour model the alloimmunization of mice with allogeneic P815 tumour cells or splenocytes IP prior to the intraperitoneal inoculation of syngeneic tumour significantly diminished the anti-tumour effects of IL-2 and LAK cell immunotherapy in 7 consecutive experiments." (PMID 2444243, 1987). "Moreover, the probiotic-based delivery system also allowed for a more sustained release of IL-2, which may contribute to prolonged immune activation in the tumor microenvironment." (PMID 41355950, 2026). "IFN-γ and IL-2, secreted by CD4 + Th1 cells, trigger the activation of DCs and enhance the cross-presentation of tumor-associated antigens (TAAs), thereby priming anti-tumor CD8 + T cells and supporting their differentiation into mature CD8 + cytotoxic T lymphocytes (CTLs)." (PMID 41582199, 2026). "Fibroblast activation protein (FAP) IL2 variant (FAP-IL2v, also referred to as simlukafusp alfa or RO6874281) is a novel, monomeric, immune-cytokine designed to overcome the limitations of wild-type IL2 by selectively promoting immune responses in the tumor microenvironment." (PMID 39895413, 2025). "Recent studies demonstrate that CAR-T cells armored with Superkine IL-2 and IL-33 can remodel the tumor microenvironment, enhance antitumor immunity, and suppress the growth of multiple solid tumors, with evidence suggesting that this combination may also mitigate antigen-loss–driven resistance." (PMID 41584600, 2025). "In addition, CC-3 induced secretion of antitumor cytokines (IFN-γ, TNF, IL-2) and effector molecules (granzymes, perforin, and granulysin), which are known to promote tumor cell death, and also induced potent and long-lasting tumor cell lysis by the activated T cells." (PMID 40707958, 2025). "Notably, α-HB subtype 2 exhibited significant enrichment in various immune and inflammatory pathways, including regulation of response to tumor cells, synaptic vesicle localization, and multiple interleukin-mediated signaling pathways (such as IL-6, IL-4, IL-2, and IL-15)." (PMID 41041634, 2025). "Over the years, IL-2 has been administered in combination with other immunotherapies, such as pembrolizumab (anti-programmed cell death protein 1 antibody) or adoptive cellular therapy (tumor-infiltrating lymphocyte therapy), to reduce severe toxic effects and optimize the therapeutic impact." (PMID 41150778, 2025). "In contrast, IL-2 may inadvertently expand immunosuppressive Tregs, dampening anti-tumor responses." (PMID 41374974, 2025). "Interestingly, endogenous IL2 appears to be inactivated in the acidic tumor microenvironment." (PMID 40397803, 2025). "Together, these findings suggest that tumor- and stromal-derived lncRNAs may disrupt IL-2-mediated immune activation at multiple levels—both by reducing IL-2 production and by impairing IL-2 receptor signaling—thereby contributing to immune evasion within the tumor microenvironment." (PMID 40429961, 2025). "Therefore, the observed IL-2 decline may facilitate tumor immune evasion by limiting effective cytotoxic responses." (PMID 41614846, 2025). "Interestingly, in preclinical models, TIM-3+/PD-1+ tumor-infiltrating lymphocytes (TILs) are characterized by significantly impaired proliferation and reduced cytokine production (IL-2, tumor necrosis factor [TNF], and IFN-γ) with a more severe exhausted phenotype than TIM-3−/PD-1+ TILs." (PMID 40508202, 2025). "However, within the TME, they promote cancer progression by inhibiting anti‐tumour responses through IL‐2 secretion which modulates NK cells, impairing function, or directly by inhibiting antigen presenting cells (APCs) resulting in blockade of cytokines secretion and hence T cell activation." (PMID 39308084, 2025). "This complex behavior may reflect the multifaceted nature of IL-2 in immune regulation, as it influences multiple immune cell types across different phases of tumor progression, potentially through mechanisms involving the activation of the VEGF signaling pathway." (PMID 40869161, 2025).